PAX3 (paired box 3)
Diseases named in the same sentence as PAX3 in open-access papers (continued):
Sharing a sentence is not in itself a finding about the gene and the disease.
spina bifida (8 papers, 2015 to 2025). A congenital neural tube defect in which vertebrae are not fully formed. "Nevertheless, the severity of spina bifida associated with PAX3 deletion warrants further investigation." (PMID 41141997, 2025). "A study described a fetus with severe spina bifida, including myelomeningocele and Arnold–Chiari malformation, which was caused by a missense variant in PAX3 (c.124G > C.pGly42Arg)." (PMID 41141997, 2025). "Among mouse genetic models, exencephaly and/or spina bifida arise in splotch mice, carrying mutations of the paired-box-domain-containing transcription factor Pax3." (PMID 31636139, 2019). "The Pax3 gene and the EphA4 gene act in concert with each other in causing spina bifida due to interstitial deletion at position 2q36." (PMID 28286691, 2017). "In particular, the closed form of spina bifida was partly due to reduced Pax3 and Cdx4 gene expression in the posterior dorsal neural tubes of Gpr161 mutant embryos with decreased Wnt signaling, whereas Shh signaling was increased." (PMID 37885410, 2023). "This is consistent with a delay in PNP closure in Pax3 heterozygotes and the small percentage of spina bifida observed in these embryos." (PMID 27114066, 2016). "Arguing against a primary effect in which the presence of neuronal cells causes spina bifida, abnormal neuronal differentiation was not apparent in the spinal neuroepithelium of Pax3 mutants at E9.5." (PMID 31636139, 2019). "A 5-bp deletion in exon 5 of the PAX3 gene was reported in a patient with spina bifida." (PMID 30665459, 2019). "In contrast, the results from a case-control study including 74 infants with spina bifida and 87 non-malformed controls indicated that variants in PAX3 were not strong risk factors for human spina bifida." (PMID 30665459, 2019). "In detail, lineage-specific deletion of PAX3 by G protein-coupled receptor 161 (Gpr161) knockdown in mice led to cranial vault and facial bone hypoplasia, vertebral abnormalities, and the closed form of spina bifida during embryonic development, likely mediated by decreased Wnt/β-catenin signaling." (PMID 41141997, 2025). "Exon sequencing of PAX3 in 114 cases with spina bifida also identified two common variants; however, without unaffected individuals, the influence of these variants on the risk of spina bifida could not be determined." (PMID 30665459, 2019). "Our results imply that a methylation change in the body region of PAX3 may be an epigenetic component of human NTDs, which is reminiscent with findings for the HOXB7 gene in a myelomeningocele (spina bifida) case-control study." (PMID 30665459, 2019).
craniofacial-deafness-hand syndrome (7 papers, 2016 to 2025). "PAX3 mutations have also been reported in craniofacial-deafness-hand syndrome (CDHS), which is characterized by nasal bone hypoplasia or aplasia, hypertelorism, hearing loss, and hand anomalies." (PMID 40869162, 2025). "Pathogenic PAX3 deletions are known to cause embryonic NC dysplasia and can lead to craniofacial-deafness-hand syndrome (CHDS), underscoring its critical developmental functions and its alignment with the observed phenotypic spectrum observed in this family." (PMID 41141997, 2025). "PAX3 mutations have also been described in craniofacial-deafness-hand syndrome (CDHS), a disorder with symptoms that include hand abnormalities, small or absent wrist and nasal bones, hearing loss, and other facial anomalies." (PMID 38473380, 2024). "The unique association of Craniofacial-Deafness-Hand Syndrome with cardiovascular anomalies due to a PAX3 variation provides valuable insights into the genetic underpinnings of this rare condition." (PMID 39850491, 2024).
embryonal rhabdomyosarcoma (7 papers, 2013 to 2026). A poorly circumscribed morphologic variant of rhabdomyosarcoma. "Whereas Pax3:Foxo1a expression was unaltered, biomarkers of aRMS versus embryonal rhabdomyosarcoma were both increased, questioning whether these diagnostic markers are reliable in the context of Rb1 loss." (PMID 24274149, 2013). "Although embryonal rhabdomyosarcoma most likely arises from myoblasts, both markers of quiescent satellite cells, e.g., PAX3, PAX7, or HEYL, and markers of activated satellite cells, including MYOD1, are frequently expressed." (PMID 31941033, 2020). "Genome-wide gene expression in Pax3:Foxo1a,Rb1 tumors more closely approximated aRMS than embryonal rhabdomyosarcoma." (PMID 24274149, 2013). "It was suggested that PAX2 and PAX5 play tumor suppressor roles in ovarian cancer and leukemia, while conversely, PAX3, PAX7, and PAX6 were reported to be oncogenic in embryonal rhabdomyosarcomas and retinoblastoma." (PMID 31235851, 2019).
metastatic disease (7 papers, 2014 to 2025). "Multivariate analysis in patients with metastatic tumors, identified PAX3::FOXO1 fusion as an independent adverse prognostic factor for EFS and OS, B/BM involvement for EFS only." (PMID 39781573, 2025). "Among patients with metastatic disease, patients aged >10 years, with FP tumors, PAX3::FOXO1 fusion type and B/BM involvement, had significantly worse EFS and OS compared to patients aged ≤10 years, without B/BM involvement, FN tumors, or with PAX7::FOXO1 fusion type." (PMID 39781573, 2025). "Interestingly, while fusion subtype does not affect survival of patients presenting without clinically overt distal metastases, patients presenting with PAX3/FOXO1 metastatic disease appear to have worse outcomes than those with PAX7/FOXO1 metastatic disease." (PMID 32697014, 2020). "Interestingly, cells expressing high levels of Pax3:Foxo1a were more prevalent in metastatic tumors." (PMID 24453992, 2014). "The heterogeneity of Pax3:Foxo1a expression in primary and metastatic tumors, and enrichment in the latter, suggested that Pax3:Foxo1a might be selectively expressed in a subset of aRMS cells; alternatively, Pax3:Foxo1a expression might be temporally regulated." (PMID 24453992, 2014). "Multivariate analysis identified PAX3::FOXO1 fusion as an independent adverse prognostic factor for EFS in patients with localized disease and for EFS and OS in patients with metastatic disease, B/BM metastases for EFS." (PMID 39781573, 2025). "In metastatic disease, patients with PAX7::FOXO1 aRMS were significantly younger compared to PAX3::FOXO1 positive group (68% vs. 33% of patients ≤10 years of age), all other factors were similarly distributed." (PMID 39781573, 2025). "Pairwise analysis between Non‐Hispanic Black versus Non‐Hispanic White patients and Hispanic versus Non‐Hispanic White patients for age group, RMS histology, Intergroup Rhabdomyosarcoma Study (IRS) group, tumor invasiveness, metastatic disease, and FOXO1 fusion partner (PAX3 or PAX7)." (PMID 37081771, 2023).
osteosarcoma (7 papers, 2009 to 2025). A usually aggressive malignant bone-forming mesenchymal neoplasm, predominantly affecting adolescents and young adults. "In human SaOS-2 and U2-OS osteosarcoma cells, ectopic PAX3 expression initiated mesenchymal-epithelial transition, yet PAX3::FOXO1 expression had an even more pronounced effect." (PMID 40599857, 2025). "The inhibition of miR-489-3p contributes to the metastasis of osteosarcoma via regulating PAX3/MET signaling." (PMID 34177591, 2021). "Pax3 has also been reported to be unable to initiate myogenesis in the human Saos-2 osteosarcoma cell line and mouse endothelial cells line BEND3, and Pax7 is unable to activate myogenesis in the C3H10T1/2 multipotent mesenchymal cell line." (PMID 19221588, 2009). "Inhibition of miR-489-3p enhanced metastasis of osteosarcoma by stimulating PAX3-MET axis." (PMID 32717723, 2020).
soft tissue sarcoma (7 papers, 2013 to 2025). A malignant neoplasm arising from muscle tissue, adipose tissue, blood vessels, fibrous tissue, or other supportive tissues excluding the bones. "The pRb and Pax3:Foxo1a status may warrant investigation in pleomorphic soft tissue sarcomas currently thought to be distinct from aRMS." (PMID 24274149, 2013).
gastric cancer (6 papers, 2019 to 2024). A primary or metastatic malignant neoplasm involving the stomach. "Furthermore, miR-206 expression was downregulated in GC cells, particularly in metastatic lesions, and loss of miR-206 promoted gastric cancer metastasis through activation of the PAX3/c-Met pathway." (PMID 32219093, 2020). "miR-658 was high in gastric cancer tissue and cells, resulting in tumor metastasis via activation of the PAX3–MET pathway." (PMID 36142562, 2022). "Additionally, suppression of PAX3 affects the MET/PI3K axis to inhibit cell proliferation and angiogenesis in gastric cancer." (PMID 38955795, 2024).
neuroblastoma (6 papers, 2011 to 2026). Neuroblastoma (NB) is the most common solid, extracranial childhood tumor. "Using a RNA interference technique, the loss-of-function effects of PAX3 in neuroblastoma cells were investigated." (PMID 24188742, 2014). "Further studies targeting PAX3 gene expression in MYCN-amplified neuroblastoma cells will help to define the mechanisms associated with PAX3 gene function in this tumour." (PMID 24188742, 2014). "In this study, Pax3 and Pax7 genes were overexpressed in Neuro‐2a, the mouse neuroblastoma cell line." (PMID 33336498, 2021). "Despite the initial onset of G1 arrest, PAX3 knock-down resulted in progressively increasing apoptosis in neuroblastoma cells." (PMID 24188742, 2014). "Compared to cells transfected with control siRNA, PAX3 knock-down completely inhibited proliferation of both neuroblastoma cell lines for 5 consecutive days (P < 0.01)." (PMID 24188742, 2014). "The gene alterations confirmed by qPCR in neuroblastoma cells after PAX3 knock-down were then compared with three sets of microarray data from melanocytes 15, myoblasts and stem cells overexpressing PAX3 (unpublished data of our research group)." (PMID 24188742, 2014). "Microarray results revealed that 2894 probe sets were altered, >2.00-fold, by PAX3 siRNA#4 transfection in neuroblastoma cells." (PMID 24188742, 2014). "Migration of both types of neuroblastoma cell was significantly reduced after PAX3 down-regulation, 38.7% reduction in SH-SY5Y cells and 55.5% in SH-EP1 cells." (PMID 24188742, 2014). "We found that PAX3 is re-expressed in neuroblastoma and malignant neuroblastic (N-type) neuroblastoma cells had significantly higher PAX3 protein expression than their benign substrate-adherent (S-type) counterparts." (PMID 24188742, 2014). "Knock-down of PAX3 expression by siRNA transfection resulted in persistent cell growth inhibition in both types of neuroblastoma cell, owing to G1 cell cycle arrest and progressive apoptosis." (PMID 24188742, 2014). "The time-dependent effects of PAX3 knock-down on cell growth demonstrated that PAX3 silencing completely inhibited proliferation of both neuroblastoma cell lines." (PMID 24188742, 2014). "PAX3 knock-down significantly augmented the cytotoxic effect of chemotherapeutic agents, etoposide, vincristine and cisplatin, commonly used to treat neuroblastoma." (PMID 24188742, 2014). "Migration and invasion of both neuroblastoma cell types were markedly reduced after PAX3 down-regulation." (PMID 24188742, 2014). "In summary, this study demonstrates that PAX3 contributes to the oncogenic characteristics of neuroblastoma cells." (PMID 24188742, 2014). "Cell cycle analysis revealed that PAX3 knock-down in neuroblastoma cells initially triggered cell cycle arrest and thereafter induced progressive apoptosis." (PMID 24188742, 2014). "Taken together, PAX3 silencing induced growth inhibition by early G1 arrest and then caused irreversible block of proliferation through apoptosis in both neuroblastoma cell types, indicating that PAX3 is required for the growth and survival of neuroblastoma cells." (PMID 24188742, 2014). "Taken together, PAX3 silencing activates multiple apoptotic signalling pathways, while simultaneously inhibiting anti-apoptotic signalling pathways, thereby inducing apoptosis in neuroblastoma cells." (PMID 24188742, 2014). "Therefore, a better understanding of the role of PAX3 in neuroblastoma requires further studies, with regard to the diversity of neuroblastoma cell phenotypes." (PMID 24188742, 2014). "Moreover, PAX3 knock-down significantly sensitized neuroblastoma cells to the cytotoxic effect of chemotherapeutic drugs." (PMID 24188742, 2014). "As PAX3 is essential for neural crest-derived peripheral nervous system development, its re-expression might occur in the peripheral nervous system tumour, neuroblastoma." (PMID 24188742, 2014).
neuroblastoma (continued). "This is the first study that demonstrates that inhibition of PAX3 expression in neuroblastoma cells resulted in persistent cell growth inhibition, G1 cell cycle arrest, progressive apoptosis, migration and invasion inhibition and decreased attachment to ECM proteins." (PMID 24188742, 2014). "Some studies have examined PAX3 expression in neuroblastoma with contradictory results which could be because of (a) different approaches, some of them employed inadequate reagents or techniques, used to detect its expression 7–8." (PMID 24188742, 2014). "It is therefore possible to speculate that PAX3 silencing in neuroblastoma modulates key cell cycle regulators, thereby preventing cell cycle progression through three cell cycle checkpoints (G1/S, intra-S, and G2/M)." (PMID 24188742, 2014). "These novel findings lead us to propose that PAX3 might contribute to oncogenic characteristics of neuroblastoma cells by regulating a variety of crucial signalling pathways." (PMID 24188742, 2014). "PAX3 knock-down caused an earlier and greater apoptosis induced by drugs (etoposide, vincristine and cisplatin) in both cell lines than an individual drug itself, suggesting that re-expression of PAX3 might contribute to drug resistance in neuroblastoma." (PMID 24188742, 2014). "Thus, PAX3 signalling seems to be important for neuroblastoma metastasis." (PMID 24188742, 2014). "The study which detected PAX3 mRNA expression used a more sensitive RT-PCR technique, whereas less sensitive riboprobes were used in another study which failed to obtain detectable PAX3 signals in neuroblastoma cell lines." (PMID 24188742, 2014). "However, the combined effects of PAX3 inhibition and chemotherapeutic drugs were tested only in MYCN-non-amplified neuroblastoma cells in this study, and MYCN is frequently amplified in advanced stage neuroblastomas with chemotherapy resistance." (PMID 24188742, 2014). "SK-N-SH neuroblastoma cell was shown to express RET, NKX2-1, PHOX2B, but not SOX10, PAX3." (PMID 21677782, 2011).
congenital hydrocephalus (5 papers, 2016 to 2025). Hydrocephalus that is present at birth. "Another study in mice provided evidence that PAX3 haploinsufficiency is a likely risk factor for the pathogenesis of congenital hydrocephalus." (PMID 41141997, 2025). "This indicates that, like compound Pax3/7, heterozygotes that display partially penetrant congenital hydrocephalus, Pax3neo/Δ5 that lack compensatory Pax7 revealed that cranial dysmorphogenesis can be caused via collective Pax3 and Pax7 deficiencies." (PMID 35645295, 2022). "By examining Pax3 conditional mutants, we established abnormal narrowing of the third ventricle as a novel mechanism that leads to early onset congenital hydrocephalus, caused by stagnation of cerebrospinal fluid in the ventricles." (PMID 26949601, 2016). "Only conditional mutants generated using Pax7−Cre or Wnt1-Cre developed early onset congenital hydrocephalus due to stenosis of the third ventricle, suggesting that loss of neuroepithelial Pax3 is sufficient to disturb third ventricle morphogenesis." (PMID 26949601, 2016). "Taken together, these data suggest that PAX3 haploinsufficiency is a likely risk factor associated with the pathogenesis of congenital hydrocephalus in patients, as well as in animal models." (PMID 26949601, 2016). "Furthermore, consistent with the overlapping expression pattern of Pax3 and Pax7 in early cranial neuroepithelium, we demonstrated a combinatorial role, as compound Pax3/Pax7 heterozygotes display partially-penetrant congenital hydrocephalus." (PMID 26949601, 2016). "Moreover, Pax3 cKOs demonstrated that NC-specific deletion is sufficient to cause DORV/VSDs and death at birth, and that restricted deletion within the neuroepithelium causes congenital hydrocephalus." (PMID 34355692, 2021).
cutaneous melanoma (5 papers, 2016 to 2025). A primary melanoma arising from atypical melanocytes in the skin. "Miskolczi and colleagues found that the presence of fibroblast tumor growth factor-β suppressed YAP/PAX3-mediated MITF expression and was associated with a dedifferentiated phenotype in cutaneous melanoma." (PMID 39804140, 2025). "PAX3 expression is highly enriched in cutaneous melanoma compared with >170 other cancer types." (PMID 26977879, 2016).
metastatic melanoma (5 papers, 2012 to 2021). A melanoma that has spread from its primary site to another anatomic site. "The results demonstrated that CTCs from metastatic melanoma patients were highly heterogeneous and commonly expressed stem-like markers such as PAX3 and ABCB5." (PMID 28978038, 2017). "Furthermore, PAX3 mRNA expression was significantly higher in adult melanocytes compared to both primary and metastatic melanoma cells (p = 0.004, p = 0.005, respectively)." (PMID 25880082, 2015). "We found that several gene sets had a similar, albeit relatively low, frequency of correlated gene pairs in all three of the A375, primary and metastatic melanoma datasets – e.g. E2F1, PAX3, CREBP, cell cycle and DNA repair gene sets." (PMID 22536322, 2012).
folate deficiency (4 papers, 2010 to 2019). A nutritional condition produced by a deficiency of FOLIC ACID in the diet. "The Pax3 mutant (Sp2H) mouse provides a model in which to investigate the cause of NTDs that are sensitive to folate deficiency and responsive to prevention by FA." (PMID 31636139, 2019). "Pax3 mutant (splotch; Sp2H) mice provide a model in which NTDs are preventable by folic acid and exacerbated by maternal folate deficiency." (PMID 31636139, 2019). "The increased penetrance of cranial NTDs in Pax3 mutant embryos demonstrates that folate deficiency can increase susceptibility to NTDs." (PMID 19824061, 2010). "This idea received support from recent studies in which maternal folate deficiency was found to increase the rate of cranial NTDs in Pax3 (splotch; Sp2H) mutant embryos." (PMID 19824061, 2010). "Notably, Pax3 mutants (Pax3Sp2H, Pax3Sp) are among the very few models in which NTDs have been found to be both preventable by supplemental FA and exacerbated by maternal folate deficiency, imposed by diet and administration of antibiotic to remove folate-synthesizing gut bacteria." (PMID 31636139, 2019). "Unlike in Pax3 mutants, NTDs resulting from disruption of the 1C supply from mitochondrial FOCM (e.g. by mutation of Gldc or Amt) are neither FA preventable nor responsive to folate deficiency." (PMID 31636139, 2019).
glioblastoma (4 papers, 2014 to 2023). The most malignant astrocytic tumor (WHO grade IV).